ALB (albumin)
Diseases named in the same sentence as ALB in open-access papers (continued):
Sharing a sentence is not in itself a finding about the gene and the disease.
tumor (continued). "The results demonstrated these 2 albumin binder–conjugated FAPI radiotracers to have high FAP binding affinity and specificity, enhanced tumor retention, and improved radiotherapy efficacy." (PMID 34593598, 2022). "There were significant differences among the three groups in the following items: WBC, neutrophil, albumin, ALT, CRP, PNI, CAR, ALBI, CEA, CA19-9, type of hepatectomy, lymph node status, maximum tumor size, major vascular invasion, and AJCC staging." (PMID 36358877, 2022). "There are two fundamental mechanisms for the tumor accumulation of albumin: the EPR effect and receptor-mediated tumor internalization and catabolism." (PMID 35456562, 2022). "Specifically, TABNs were first anchored onto the surface of tumor cells, and then the thiol-exposed BSA molecules were introduced to link TABNs to an albumin-based net that spatially caged tumor cells." (PMID 35910806, 2022). "QUESTION: Do albumin binder–conjugated FAPI radiopharmaceuticals have high FAP specificity and provide enhanced tumor retention and improved radiotherapy efficiency?" (PMID 34593598, 2022). "An albumin level of <36 g dL−1, AFP levels of >400 ng mL−1, bilirubin levels of >17 μmol L−1, and a maximum tumor diameter of >7 cm are each given 1 point in this scoring system." (PMID 35884412, 2022). "The consistent covariables vital to the DSS included albumin, hemoglobin, PS status, SUVmax, ascites, platelet to white blood cell ratio (PWR), fibrinogen, age, white blood cell, and tumor size." (PMID 36387243, 2022). "In the univariate analysis, tumor size, total bilirubin (TBIL), albumin (ALB), ALBI-grade, AST, GGT, IL-8, PIVKA-II, and treatment with anti-PD-1 immunotherapy were significantly associated with OS." (PMID 36295504, 2022). "Based on the canonical marker gene expression, 3,085 cells were annotated as tumor cells (GPC3, EPCAM, AFP, ALB, DLK1), while 18,365 cells were designed as non-tumor cells." (PMID 35860547, 2022). "Hyaluronic acid functionalized/all-trans-retinoic acid- (ATRA) loaded albumin-based cationic NPs were prepared and evaluated in CD44 overexpressed CSCs in in vivo lung metastasized tumor models." (PMID 35163777, 2022). "The updated overall survival (OS) model includes age, neutrophil and lymphocyte counts, albumin, hemoglobin, LDH, and p-16 tumor status." (PMID 35836204, 2022). "The results show that AFP and TBIL were important variables that simultaneously met both conditions in PVTT invasion, tumor number, treatment (TACE-A or TACE-AP), and albumin." (PMID 36249011, 2022). "The HAP score integrated tumor size, AFP, bilirubin, and albumin together, and the three modified HAP series scores (mHAP, mHAP-II, and mHAP-III) were subsequently developed through various adjustments subsequently." (PMID 36776366, 2022). "In this study, multiple HCC tumours larger than 5 cm affected overall survival outcomes, whereas for tumours smaller than 5 cm, AST and albumin levels, histologic characteristics, and the extent of resection did affect the survival outcome." (PMID 35268459, 2022). "The fusion of albumin to anti-CEA successfully complemented the rapid clearance of anti-CEA, demonstrating a dramatic increase in its tumor-specific accumulation up to 4.6-fold." (PMID 35456562, 2022). "The commonly identified significant covariates were body weight (BW) on CL and VC, and albumin (ALB), tumor type, sex, and performance status (PS) on CL." (PMID 35983041, 2022). "For example, albumin NPs conjugated with low-molecular-weight protamine are designed to bind to an albumin-binding protein (e.g., SPARC and gp60) on glioma and tumor vessel endothelium." (PMID 36012269, 2022). "During circulation, EB-FAPI-02 will bind to albumin in a dynamic way, and will be released from albumin when in proximity with FAP in the tumor stroma." (PMID 34987657, 2022).
tumor (continued). "A change was observed in the biochemical parameters of blood only in mice bearing A549 tumours, whereas in combined treatment groups, a decrease in the levels of ASTL, CRE2, UREL and ALB was noticed." (PMID 35701366, 2022). "The factors between PLR and GC patients, such as sex, tumor diameter and location, R0/R1 (R2) resection, WBC (white blood cell), hemoglobin, fibrinogen, albumin, TNM, PNI, and NLR show significant relationship (all P < 0.05)." (PMID 35340978, 2022). "Sex, age, degree of differentiation, AFP, ALB, HBV, HCV, Child-Pugh score, tumor number, surgical method, MVI, postoperative treatment, postoperative surgery, postoperative TACE or HAIC and postoperative drugs were included as predictors in the PSM." (PMID 35928871, 2022). "According to the figure, the fastest and highest tumor growth was in the PBS- and albumin-receiving groups, whereas the nanoparticle-receiving group demonstrated the slowest tumor growth compared to others." (PMID 36359230, 2022). "Before PSM, the results of univariate analysis revealed that age, maximum diameter of tumor, histological type, SII, ALb, CEA, CA199, CA125, WBC count, operation method, and TNM stage were all influencing factors for the prognosis of GC patients (P < 0.05)." (PMID 34980151, 2022). "Notably, a larger tumor volume, younger age, higher histological tumor grade, higher platelet count, and higher NLR ratio were associated with a higher risk of dMMR, while a higher preoperative HB level, albumin level, and eosinophil ratio were related to a lower risk of dMMR." (PMID 36620593, 2022). "Propensity score matching was performed based on BMI, pre-operative albumin, PNI, CA 19-9, tumor size, and length of tumor–vessel contact, after which each group consisted of 40 cases." (PMID 36428767, 2022). "Missing data included 25 albumin, 11 total bilirubin, 12 AFP, 3 tumor size, 3 tumor number, and 27 MVI values." (PMID 34235600, 2021). "ALB (p = 0.004), CEA (p < 0.001), tumor location (p = 0.006) and Ki67 (p = 0.041) were statistically significant between non-LNM and LNM groups." (PMID 33789664, 2021). "89Zr bound to albumin can then accumulate in tumors via enhanced permeability and retention (EPR) effect and confound the tumor uptake signal from 89Z-oxine labeled cells." (PMID 34302002, 2021). "RSF revealed that five parameters, namely size of the tumor, BCLC-B sub-classification, AFP level, ALB level, and number of lesions, were strong predictors of survival." (PMID 33738252, 2021). "Four independent factors were incorporated in this nomogram: tumor size, TNM stage, post-operative serum albumin level, and post-operative ALRI value." (PMID 34295811, 2021). "ALB, CEA, tumor location, and Ki-67 expression level correlate with the risk of LNM in patients with G-NET." (PMID 33789664, 2021). "The two parameters outstanding from our data, which were included in the suggested ‘CLAS’ reflect tumor burden (LDH) and the patients’ nutritional status (ALB)." (PMID 34367942, 2021). "We confirmed that the key prognostic factors of HCC include current smoking, albumin, prealbumin, AFP, varicose veins of gastric fundus, BDTT, macrovascular invasion, MVI, tumor number, and maximal tumor diameter." (PMID 34976789, 2021). "Logistic regression revealed ALB (p = 0.043), CEA (p = 0.032), tumor location (p = 0.013) and Ki-67 (p = 0.041) were independent risk factors for LNM in G-NET patients." (PMID 33789664, 2021). "Ten days later, when tumour volume reached to 50 mm3, CCF642 (10 mg/kg) or albumin vehicle concomitant with cisplatin (5 mg/kg) were intraperitoneally (i.p.)administrated into nude mice." (PMID 33732415, 2021). "Compared with paclitaxel albumin nanoparticles (20 mg/kg), Nab-PTX-PA (51.16 mg/kg) had similar myelosuppressive toxicity but its anti-tumor effect was increased significantly." (PMID 34109887, 2021).
tumor (continued). "The tumor inhibition rate of 25.58 mg/kg and 51.16 mg/kg Nab-PTX-PA was higher than that of paclitaxel albumin nanoparticles (20 mg/kg), with the tumor inhibition rate of 51.16 mg/kg Nab-PTX-PA being more significant." (PMID 34109887, 2021). "Improving liver functions (ALT, albumin, T bilirubin, D bilirubin, and Alfa Fetoprotein AFP) and liver microstructure characteristics of precancerous lesion rats, and improving the acidic tumor microenvironment." (PMID 33869059, 2021). "The albumin-RTKI complexes form rapidly in the blood and travel through the circulation until they enter the blood vessels of the tumor." (PMID 33920299, 2021). "Using the univariate Cox model, age, sex, smoker, tumor size, nodal invasion, TNM stage, lymphatic invasion, vascular invasion, albumin level, and CLR were identified as significant determinants of OS." (PMID 34149913, 2021). "All those significant variables, except the ALB and the PLR, were tumor-related factors, and have been commonly considered to be associated with the long-term prognosis of ICC." (PMID 33676467, 2021). "Accordingly, a variable that combined tumor site and metastatic status was built, and each model included a term for the interaction between G8 on one hand and GPS, mGPS, CRP, albumin, and CRP/albumin ratio on the other." (PMID 34944774, 2021). "The patients in NsA group had lower levels of ALB (p = 0.022), higher levels of AFP (p = 0.034), higher levels of AST (p < 0.001), longer PT (p = 0.0025), and larger tumor size (p < 0.001) compared with NtA group." (PMID 34643050, 2021). "Infigratinib‐treated tumours showed higher expression of the differentiation markers CYP3A4, HNF4α and albumin, indicating a reduction in stemness." (PMID 33179425, 2021). "Of particular note in our analysis, was the usefulness of combination GGT plus albumin in the low-AFP cohort, for whom there are few other validated tumor markers." (PMID 34540270, 2021). "To further investigate the mechanisms of PLGA-FAKi with regard to the improved tumor suppression of OVA-CTLs, we performed SPECT imaging using 99mTc-labeled human serum albumin (99mTc-HSA) as a tumor perfusion marker." (PMID 34112200, 2021). "Several clinical features were found significantly different between the training and validation datasets including globulin (Glb), albumin-globulin ratio (AGR), tumor differentiation, T-stage, lymph node status (N-stage) and vascular invasion (VI)." (PMID 34193166, 2021). "In the multivariate analysis, including tumor location, number of metastasis before ICI, ECOG PS, and albumin levels, LIPI was an independent factor for OS (HR for intermediate, 1.43 [95%CI 0.75 to 2.74]; HR for poor, 3.50 [95%CI 1.46 to 8.40], p = 0.03)." (PMID 34359675, 2021). "Based on VIMP, we identified and evaluated five parameters, namely tumor size, BCLC-B sub-classification, AFP, and ALB levels, as well as number of lesions as strong predictors." (PMID 33738252, 2021). "Univariate and multivariate analyses were performed for age, serum albumin, ALT, AST, tumor diameter, and other clinicopathologic variables." (PMID 32026332, 2021). "We found that post‐treatment albumin level, post‐treatment NLR and overall tumour response were independent prognostic factors in patients who received definitive chemoradiotherapy." (PMID 33590710, 2021). "In tumor-bearing animals receiving sesame oil, ALP and albumin were significantly decreased, while the cholinesterase, cholesterol, and total protein were significantly increased." (PMID 34572369, 2021). "After PSM, albumin, INR, AST, AFP, HBV DNA, Edmondson grade, BCLC stage, ALBI score, PLR, NLR, capsule integrity, microvascular invasion, tumour embolus, and tumour size were identified as possible influencing factors in the univariate analysis (P<0.05)." (PMID 34149909, 2021).
tumor (continued). "They varied between the approved ICIs, but sex, Eastern Cooperative Oncology Group (ECOG) PS, body weight, tumor type, tumor burden, baseline lactate dehydrogenase (LDH), estimated glomerular filtration rate, and albumin can be considered in the differences." (PMID 34205484, 2021). "Paclitaxel albumin nanoparticles (20 mg/kg), Nab-PTX-PA (25.58 mg/kg) and Nab-PTX-PA (51.16 mg/kg) had different anti-tumor effects." (PMID 34109887, 2021). "Taking into account availability and expense, an equivalent BAA-BS model was established based on total bilirubin, albumin, AFP, BMI and largest tumor size." (PMID 33531992, 2021). "Fluorescent bovine serum albumin (BSA) encapsulated gold nanoclusters were conjugated onto the surface of nanogels, followed by functionalization of tumor targeting peptide iRGD onto the BSA for tumor targeting." (PMID 34073626, 2021). "Inspired by the promising example of folate radioconjugates, attempts to translate the “albumin-binder concept” to PSMA radioligands and other tumor-targeting agents were undertaken by several research groups." (PMID 32949253, 2021). "In the current work, the significance of serum levels of GGT alone or in combination with other liver function parameters, especially albumin, has been examined in relation to HCC survival and to clinical tumor characteristics." (PMID 34540270, 2021). "By interacting with albumin, the HMCD-carrier can reach the tumor vasculature passively through the EPR effect." (PMID 34141613, 2021). "In another study, an albumin–PTX conjugate was incorporated into mesoporous silica NPs, followed by loading into Mφs to overcome poor drug accumulation within the tumor." (PMID 33898169, 2021). "The AUC area for ALB, CEA, tumor location and Ki-67 was 0.707, 0.642, 0.618 and 0.657, respectively." (PMID 33789664, 2021). "The two groups differed significantly in terms of age, maxim tumor size, number of tumors (solitary/multiple), macrovascular invasion, BCLC stage, TNM stage, ALT, ALB and Child–Pugh grade." (PMID 35117990, 2021). "Higher ALRI level positively correlated with larger tumor size, higher tumor node metastasis (TNM) stage, and inversely with lower albumin level and shorter OS and DFS." (PMID 34295811, 2021). "Significant variables identified in previous univariate analysis (including age, ALB, CEA, INR, TT, tumor location, Ki67 and CgA) were enrolled into the regression model." (PMID 33789664, 2021). "The univariate analysis identified tumor size, portal vein invasion, hepatic vein invasion, extrahepatic spread, AFP, AST, albumin, NLR, and PLR as potential prognostic factors for PFS." (PMID 34124139, 2021). "As a result of the greater tumor burden, the unfavorable response cohort exhibited worse liver function markers (e.g., ALBI grade, AAPR, CP, albumin, and alkaline phosphatase) and BCLC stage at baseline than the favorable response group." (PMID 34336728, 2021). "This normogram includes six pre-Y90 treatment parameters: number of extrahepatic disease sites, carcinoembryonic antigen (CEA), albumin, alanine aminotransferase (ALT) level, tumor differentiation level and SUVmax of the two largest tumor diameters." (PMID 34885047, 2021). "Before PSM, albumin, INR, AST, ALT, AFP, HBV DNA, Edmondson grade, BCLC stage, ALBI score, PLR, NLR, capsule integrity, microvascular invasion, tumour embolus, tumour size, and SM were the possible influencing factors in the univariate analysis (P<0.05)." (PMID 34149909, 2021). "The CFP scoring system is a combination of tumor markers (CEA), inflammatory factors (lymphocytes and fibrinogen), and nutritional factors (albumin)." (PMID 33849545, 2021). "This suspension formulation, utilized the natural properties of albumin to reversibly bind PTX, transport across the endothelial cell and accumulate PTX in tumor tissues, was be believed a successful application of prodrug‐nanotechnology." (PMID 34323373, 2021).
tumor (continued). "The PRG consisted of two non-tumor-specific SIR markers platelet-to-lymphocyte ratio (PLR) and albumin (ALB), which were both the independent predictors of overall survival (OS)." (PMID 33676467, 2021). "The tumor number and size, the preoperative alpha-fetoprotein (AFP) level, the preoperative albumin-bilirubin (ALBI) grade and gender were first combined as independent predictors to first validate the pre-ERASL model." (PMID 33924061, 2021). "These analyses also indicated that RFS was significantly related to albumin <3.5 g/dL, ChE <250 IU/L, ICGR15 ≥15%, AFP ≥20 ng/mL, PIVKA‐II ≥100 mAU/mL, RHBPP ≥1.036, and tumor size ≥5 cm, except in cases of the simple nodular type." (PMID 33490612, 2021). "The HAP score takes into account four parameters (ALB, TBIL, AFP, and tumor size) and is divided into four levels (HAP-A, HAP-B, HAP-C, and HAP-D)." (PMID 34745962, 2021). "In an example of serum albumin loaded with chemotherapy drugs, HSA pre-modified with either chlorin e6 (Ce6) or cyclic Arg-Gly-Asp (cRGDyK) peptide was used to load PTX for tumor-targeted PDT and chemotherapy." (PMID 34869202, 2021). "The univariate analysis revealed 10 significant factors, including gender, primary tumor type, PS, NLR, MLR, PLR, albumin, alkaline phosphatase (ALP), liver metastasis, and clinical tumor response." (PMID 34201707, 2021). "Among them, post‐treatment albumin level, post‐treatment NLR and overall tumour response to definitive chemoradiotherapy remained significant in multivariate analysis." (PMID 33590710, 2021). "Tumour sections were stained for markers of hepatocyte differentiation, such as CYP3A4, HNF4α and albumin." (PMID 33179425, 2021). "Polymer-based NPs composed of albumin, and polyethyleneimine-PEG demonstrated tumor proliferation inhibition." (PMID 32793488, 2020). "Univariate analyses indicated that several clinical indexes, such as vessel invasion, perineural invasion, tumor length, TNM stage, CRP, ALB, NLR, LDH and GRIm-Score, were significant predictors of CSS." (PMID 32047540, 2020). "There were significant differences regarding present illness (tumour), CRP (mg/dL), albumin (mg/dL), number of catheterizations catheterization times, total unused time (locked time), insertion anatomical site, dominant vein, and hyperosmotic solution." (PMID 32005839, 2020). "Given the overlap of four prognostic parameters (albumin, bilirubin, AFP and tumour size) which are dichotomized in the HAP and SAP scores, this is not unexpected." (PMID 31579990, 2020). "The higher levels of ALB and AAT mRNAs in 3DP-HepG2 model than those in planar cultured cells indicated that 3D printed tumor models had stronger liver function." (PMID 32582546, 2020). "Baseline variables pre-initial TACE associated with improved survival in patients undergoing repeat TACE included single tumour (p = 0.043), BCLC stage A (p = 0.026) and higher serum albumin (p < 0.001)." (PMID 32471447, 2020). "Not only in intermediate areas, but also in CC or CLC areas of murine tumor, tumor cells with intermediate phenotype featured by co-expressing CK19 and ALB were found." (PMID 32190288, 2020). "Meanwhile, the hub genes from the DEGs between T and LM groups (ALB, FGG, AHSG, TF, and GC) also showed marked alterations in the correlations, indicating potential mechanisms involved in the tumor metastasis." (PMID 32496505, 2020). "Controversy still exists on what can indicate a poor BL prognosis, like old age, high IPI score, tumor diameter of >10 cm, high LDH level, albumin decrease, higher clinical stage, BM, and CNS invasion." (PMID 32000356, 2020). "In the MMTV-PyMT and FaDu tumors, sub-regions within the tumor demonstrated inverse relations between glucose utilization measured with [18F]FDG and the uptake of albumin-bound [68Ga]ABY-028." (PMID 32960353, 2020).